TARBP1 (tRNA guanosine 2 -O-methyltransferase TARBP1)
Description:
S-adenosyl-L-methionine-dependent 2'-O-ribose methyltransferase that catalyzes the formation of 2'-O-methylguanosine at position 18 (Gm18) in a subset of tRNA. Selectively mediates Gm18 methylation of tRNAGln-TTG/CTG and tRNASer-TGA/GCT. Gm18 modification can enhance the stability of modified tRNAs. (Microbial infection) In case of infection by HIV-1, it binds to the loop region of TAR RNA, a region also bound by RNA polymerase II. Binding of TARBP1 and RNA polymerase II to HIV-1 TAR RNA is mutually exclusive, suggesting that TARBP1 may function alone or in conjunction with HIV-1 Tat to disengage RNA polymerase II from HIV-1 TAR RNA.
Synonyms: TRP-185; TRM3; TRP185; TRMT3
Tractability: Small molecule: a structure with a bound ligand is known; it has a high-quality binding pocket. PROTAC: ubiquitination databases record sites on it; its protein half-life has been measured.
Target class: Other nuclear protein
Gene: Protein-coding gene on chromosome 1 (234,391,313 to 234,479,197, reverse strand). Ensembl gene ENSG00000059588.
Subcellular location (Human Protein Atlas): Nuclear speckles
Gene Ontology:
Molecular function: tRNA (guanine(18)-2'-O)-methyltransferase activity; RNA binding; tRNA (guanine) methyltransferase activity; RNA methyltransferase activity; S-adenosylmethionine-dependent methyltransferase activity
Biological process: tRNA methylation; regulation of transcription by RNA polymerase II; RNA processing
Cellular component: nucleus
Genetic constraint (gnomAD): Loss-of-function variants: 104 observed, 128.83 expected, observed/expected ratio (o/e) 0.81, 90% interval 0.69 to 0.95. The upper end of that interval is the gene's LOEUF score, 0.95, which puts it in group 4 of 6, group 1 being the genes least tolerant of losing a copy. Missense variants: 1,818 observed, 1,616.6 expected, observed/expected ratio (o/e) 1.12, 90% interval 1.08 to 1.17. Synonymous variants: 709 observed, 629.19 expected, observed/expected ratio (o/e) 1.13, 90% interval 1.06 to 1.2.
Homologues: Orthologues: chimpanzee TARBP1 (99% identical), macaque TARBP1 (97% identical), pig TARBP1 (86% identical), rabbit TARBP1 (86% identical), dog TARBP1 (82% identical), guinea pig TARBP1 (76% identical), mouse Tarbp1 (72% identical), rat Tarbp1 (70% identical), tropical clawed frog tarbp1 (54% identical), zebrafish tarbp1 (41% identical). Paralogues in human: MRM3 (5% identical), MRM1 (5% identical).
Diseases named in the same sentence as TARBP1 in open-access papers:
TARBP1 is named in the same sentence as 6 diseases in open-access papers, as found by Europe PMC text mining. Sharing a sentence is not in itself a finding about the gene and the disease. The quoted sentences say what the papers report.
Cirrhosis (1 paper, 2020). A chronic disorder of the liver in which liver tissue becomes scarred and is partially replaced by regenerative nodules and fibrotic tissue resulting in loss of liver function. "We finally selected three upregulated hub genes (KPNA2, TARBP1, and RNASEH2A) for which expression was systematically increased from normal liver to cirrhosis and HCC tissues based on the GSE89377 dataset." (PMID 32213663, 2020).
hepatocellular carcinoma (1 paper, 2023). A malignant tumor that arises from hepatocytes. "The expression of the TARBP1 gene is upregulated in hepatocellular carcinoma (HCC), and its expression is associated with the pathological severity of the disease." (PMID 37375208, 2023).
cancer (6 papers, 2006 to 2024). A tumor composed of atypical neoplastic, often pleomorphic cells that invade other tissues. "Of them, TARBP1, KIAA1429, MTEEL3, RBM15, RBM15B, and TARBP1 had extensive somatic mutation among pan-cancers." (PMID 36707911, 2023). "Regarding the effects of its aberrant expression, TARBP1 is highly expressed in several cancers, including HCC and NSCLC125,126." (PMID 38689093, 2024). "However, the precise mechanism by which TARBP1 affects cancer progression was not fully investigated in the related studies." (PMID 38689093, 2024). "Three corresponded to genetic determinants of genetic syndromes (MTMR, DISC1, MTX1) and the three others bore functions with no obvious link to cancer (NENF, ENSA, TARBP1)." (PMID 17060936, 2006).
tumor (2 papers, 2020 to 2021). "SCAMP3 level was positively correlated with disease stages and tumor grades and negatively correlated with patient survival; SOX4, STK39, TARBP1, and TDRKH can be regarded as potential prognosticators and therapeutic targets for HCC." (PMID 34277395, 2021). "A review of the literature found that six of the 12 upregulated genes (KPNA2, CDK1, TARBP1, PRC1, FEN1, and MCM6) were overexpressed in HCC tissue compared to levels in non-tumor tissue based on immunohistochemical staining." (PMID 32213663, 2020).
TARBP1 also shares sentences with these, for which no sentence is quoted: colorectal adenoma (1 paper); infection (1).